MYC (MYC proto-oncogene, bHLH transcription factor)
Diseases named in the same sentence as MYC in open-access papers (continued):
Sharing a sentence is not in itself a finding about the gene and the disease.
cancer (continued). "Studies have found that abnormal expression of MYC exists in cancer, and the expression of MYC is closely related to genes regulating glucose metabolism, such as GLUT1, HK2, PFKM, etc.." (PMID 37663261, 2023). "Systems analyses of the regulatory networks in cancer have shown that SP1, HIF-1, and MYC belong to a group of TFs that function as master regulators of cancer." (PMID 37998757, 2023). "In this review, we provide an overview of the interactions and collaborations of SP1, HIF1A, and MYC in the regulation of various cancer-related genes, and their potential implications in the development of anticancer therapy." (PMID 37998757, 2023). "Elevated expression of MYC frequently occurs in human cancers and is correlated with tumor aggression and poor clinical outcome." (PMID 36765885, 2023). "In this study, after the pharmacological combined inhibition of PLK1 and ACLY, the mRNA expression levels of SREBF1 and MYC were significantly decreased in most pan-cancer cell lines." (PMID 37958642, 2023). "Both pluripotency (NANOG and MYC) and mitochondrial activities are positively correlated with stemness scores in single cancer cells." (PMID 37463926, 2023). "Some of them are involved in the maintenance of cancer stem cells (CSCs), such as MYC (Myc proto-oncogene protein), CCND1 (CyclinD1) and ABCB1 (ABC multidrug transporter)." (PMID 37237497, 2023). "Aberrations or upregulation of MYC-related pathways by alternate mechanisms are observed in the vast majority of cancers." (PMID 37554307, 2023). "An example of the translational applicability of our preclinical models is the prediction of clinical responses to drugs targeting the genetic drivers of MM progression, including several MAPK and MYC inhibitors currently being tested in cancer patients." (PMID 36928817, 2023). "As above reported, NF-kB plays an important role in HR-HPV induced cancer, since this pathway also leads to cyclin D1 and c-MYC transcription, which in turn also plays an important role in cancer progression." (PMID 37108333, 2023). "AC cancer cells were specifically enriched in signalling pathways related to MYC and oxidative phosphorylation." (PMID 36690709, 2023). "Hierarchical clustering of the enriched gene sets revealed several specific patterns, including elevation of mitotic pathways, such as MYC targets, mitotic spindle, and DNA repair, in all cancer tissues compared with those in normal tissues." (PMID 35726701, 2023). "In order to precisely treat MYC-dependent cancers by oral drug administration, special measures are required to enhance drug bioavailability and patient compliance." (PMID 36969025, 2023). "Due to the multifunctional activities of MYC in cellular functions, cancers with MYC activation elicit many of the important hallmarks essential for autonomous neoplastic growth." (PMID 37998757, 2023). "We and others have shown that ectopic MYC disrupts the molecular clock machinery across several types of cancer models." (PMID 37639465, 2023). "MYC is known to induce ARF levels and ARF is often silenced or mutated in cancer and/or is negatively selected during MYC-driven transformation." (PMID 36869047, 2023). "Noteworthy, c-MYC is one of the most frequently deregulated driver genes in human cancer and for decades it has been investigated as a possible target of novel therapeutic approaches." (PMID 36536122, 2023). "The glucose transporter SLC2A1 (GLUT1) is a key target of MYC and allows increased glucose uptake via cancer cells by enhancing its activity." (PMID 37443779, 2023). "HDAC and PI3K inhibitors have been reported to reduce MYC protein expression and have synergistic anti-cancer effects." (PMID 37580826, 2023).
cancer (continued). "The guanosine biosynthetic enzymes, inosine monophosphate dehydrogenases (IMPDHs), are frequently upregulated by MYC in cancers." (PMID 37443779, 2023). "An increased AMP-activated protein kinase (AMPK) or c-MYC signaling, very common in cancer cells, also enhance the glycolytic flux through GLUT isoforms regulation or by inducing PFK or HK overexpression." (PMID 37345199, 2023). "We explored the GSCA to determine the drug sensitivity profile data of c-Met/GSK3β/MYC/CCND1 against different cancer cell lines." (PMID 36672275, 2023). "The transcription factor MYC, which is highly expressed during early development and silenced in somatic cells, is overexpressed in almost 70% of cancers." (PMID 36866275, 2023). "Expression of this lncRNA correlates with expression of the MYC oncogene in different types of cancer." (PMID 38203731, 2023). "Here, we will overview the major achievements made in the last decades towards the discovery of a new class of anticancer drugs targeting G-quadruplexes in the c-MYC promoter of cancer cells." (PMID 36979947, 2023). "Our collective data therefore suggest that ssCHK1 and ssBRD4 exhibit anticancer properties in combination in MYC‐driven cancers and have the potential to serve as therapeutic agents following subsequent downstream optimization for in vivo delivery." (PMID 36684069, 2023). "Apart from Raf and MEK, PKCγ can interact with ERK which triggers cancer cell proliferation through many proteins, including cyclin D and MYC, to name a few." (PMID 37344815, 2023). "For example, small molecule inhibitors such as I-BET, JQ1, and MMS417 have been identified as transcriptional repressors of MYC, and these small molecule inhibitors can significantly inhibit cancer progression." (PMID 37631029, 2023). "MYC overexpression in cancer cells contributes to the formation of a high number of MYC/MAX dimers that invade transcriptionally active chromatin sites." (PMID 36830948, 2023). "CLK inhibitors, such as T-025, are being investigated as anticancer drugs because MYC amplification makes cancer cells vulnerable to them." (PMID 37443779, 2023). "BRD proteins exert a significant influence on regulating many critical oncogenes, including MYC, inside cancer cells." (PMID 37926722, 2023). "In large B-cell lymphoma (DLBCL), miR-665 has been shown to suppress the growth of cancer cells by targeting MYC and LASP1." (PMID 37894282, 2023). "What is more, the unique metabolic pathway dependencies of MYC-driven cancers offer promising therapeutic strategies for MPCs." (PMID 38136334, 2023). "The proto-oncogenic transcription factor MYC is deregulated in almost all human cancers, especially HCC, and high levels of MYC are associated with poor prognosis." (PMID 37739936, 2023). "We performed high‐throughput screens with these libraries in four MYC‐dependent cancer cell lines—K562, ST486, HepG2, and MCF7—which revealed several essential E‐boxes and genes." (PMID 37519063, 2023). "Given its pervasive role in cancer biology, MYC down‐regulation has become an attractive cancer treatment strategy." (PMID 36639831, 2023). "Together, this large body of evidence indicates that MYC upregulation promotes cancer and aging, while downregulation promotes healthy aging and increased lifespan." (PMID 37908640, 2023).
cancer (continued). "MYC is a proto-oncogene and a pleiotropic transcription factor, and clones with high MYC expression levels arise as subclones during malignant progression in a range of cancers, and generally correlate with higher grade and poor survival." (PMID 37946084, 2023). "When the promoter of PVT1 is non-functional, the intragenic enhancers rewire it towards the promoter of MYC with a topological rearrangement in the 3D genome that boosts the oncogenic expression of MYC, thus enhancing cancer cell proliferation." (PMID 36901971, 2023). "MDM2-binding protein (MTBP) is the transcriptional target of MYC oncogene, found to be overexpressed in various cancers including TNBC." (PMID 37174125, 2023). "To investigate the effect of Omomyc on the expression of genes directly regulated by MYC, we resorted to the signature of 100 direct MYC targets—conserved in a variety of cancer cell lines—described by Muhar and coworkers." (PMID 36830948, 2023). "The discovered direct relationship between USP45 and MYC can be used for suppressing MYC and cancer stemness." (PMID 36765885, 2023). "Low protein (LP) diet weakened the mTORC1 signaling in MYC-PyMT cancer cells, reversing the competitive fitness between MYC-PyMT and Control-PyMT tumors." (PMID 37884533, 2023). "BRD4 has attracted attention as a promising anti-cancer drug target due to its strong effect on expression of the transcription factor MYC, which is a well-known pro-oncogenic master regulator and a major driver of wide variety of cancers." (PMID 36711038, 2023). "MYC’s ability to protect cancer cell genomes from DNA damage can prevent catastrophic damage and promote survival in the face of genomic instability, which can support oncogenic transformation." (PMID 37755397, 2023). "The GSVA score revealed that ORC6 was positively correlated with some cell proliferation pathways (e.g., G2M checkpoint, E2F targets and MYC targets v1–2), “DNA Repair” pathway and “unfolded protein response” pathway in almost all cancers." (PMID 36978046, 2023). "In cancer, hnRNPK binds to the promoter regions of MYC (MYC proto-oncogene) and SRC (SRC proto-oncogene) to elevate their transcription or binds to their mRNAs to control translation." (PMID 36735291, 2023). "Understanding the upstream factors leading to MYC upregulation would further diversify the options to target MYC in mitochondrial disease and potentially also in cancer." (PMID 37731815, 2023). "MYC is one of the most commonly deregulated proteins in multiple cancer cells but is difficult to target with appropriate drugs." (PMID 36969025, 2023). "Additional pan-cancer bioinformatic analyses correlate the downregulation of HNRNPH expression and the upregulation of HNRNPF with the MYC hallmark score." (PMID 37399401, 2023). "Deregulated expression of the MYC oncoprotein has been shown to alter expression of molecular clock genes, leading to a disruption of molecular clock oscillation across cancer types." (PMID 37639465, 2023). "SP1, HIF-1, and MYC are three major TFs that play important roles as master regulators of cancer, so the next question is—what are these TFs and how do they benefit cancer as regulators of gene expression?" (PMID 37998757, 2023). "CDK12/13 activity is particularly important in cells with high transcriptional rate, such as cancer cells harboring MYC amplification or up-regulation." (PMID 37599362, 2023). "In conclusion, as a key metabolic and cell cycle regulator, MYC alterations have long been the focus of cancer research." (PMID 37443779, 2023). "The FA antitumor potency positively correlated with MYC levels, presenting it as a potential drug for the treatment of cancers with MYC amplification." (PMID 36831595, 2023). "PVT1, a well-known oncogenic lncRNA, is usually coexpressed with MYC (MYC proto-oncogene) and is vital for increasing the expression of MYC in cancer." (PMID 37255541, 2023).
cancer (continued). "In contrast, cancer cells, particularly those driven by MYC, engage in upregulated nutrient uptake and biosynthesis." (PMID 37639465, 2023). "The MCODE analysis identified gene clusters for each cancer type with MYC, PCNA, PARP1, IDH1, FGF10, PTEN, and CCND1 as hub genes with high connectivity." (PMID 35001007, 2022). "Accordingly, c-MYC- or N-MYC-driven cancer cells, including TNBC, are more sensitive to BRD4 inhibition." (PMID 36139513, 2022). "The introduction of let-7a into cancer cells restored proper regulation of RAS and c-MYC expression and limited the proliferation of cancer cells." (PMID 35269947, 2022). "In MYC-dependent cancers, interference of chromatin-dependent signal transduction with RNA polymerase II (RNA Pol II) and inhibition of RNA Pol II transcription initiation and elongation are therapeutic principles in malignancies." (PMID 35757006, 2022). "MYC is a gene frequently involved in cancer, and it is one of the four genes (in addition to Oct4, Sox2, and Klf4) that can reprogram fibroblasts to become pluripotent stem cells." (PMID 34991589, 2022). "According to these authors, this compound targets with high affinity the c-MYC DNA G4 (in comparison with other G4 structures) and ultimately downregulates MYC transcription in cancer cells." (PMID 35337098, 2022). "Oncogenic MYC is dysregulated or aberrantly expressed in approximately 70% of human cancers, including breast, bone, brain, B-cell lymphoma, colon, cervix, lung, pancreatic, and prostate tumors, with correlating poor prognosis and aggressive disease." (PMID 36613820, 2022). "Modulating the expression or function of the MYC protein is a viable therapeutic goal in an array of cancer types, and potential inhibitors of MYC with high specificity and selectivity are of great interest." (PMID 36613820, 2022). "HIF-1α and HIF-2α differ in how they regulate the highly oncogenic pathway, MYC, which is seen to be upregulated or downregulated in cancers by up to 70%." (PMID 35267567, 2022). "MYC inactivation can also trigger senescence in various cancer types and promote cancer elimination." (PMID 34687270, 2022). "In the present review, we looked into how Wnt/β-catenin affects the expression of PD-L1 and related genes like c-MYC in cancer cells and its role in the development of HPV-induced malignancy." (PMID 37305016, 2022). "For example, G4s were shown to modulate the expression of key cancer genes, such as MYC, c-Kit, BCL2, and KRAS, with their disruption resulting in pronounced expression changes." (PMID 35573091, 2022). "We therefore set out to quantify to what extent the PD-L1 mRNA level (CD274) in cancer patients can be predicted by activity of the relevant TFs MYC, HIF1A/2A, JUN, IRF1, STAT1/3, NFKB, and NRF2." (PMID 35289334, 2022). "The effects of MYC and JNK in cancer cell response to TOP1 inhibition were validated via loss-of-function and gain-of-function experiments." (PMID 35844787, 2022). "MYC is frequently overexpressed in many cancers, and drives a cancer stem cell phenotype with enhanced cell growth, metastasis, and metabolic reprogramming." (PMID 36207293, 2022). "More recently, WDR5 was found to physically interact with the proto-oncogene and transcription factor MYC to guide its chromatin binding and transcriptional activation, suggesting that WDR5 is a tractable target for MYC-driven cancers." (PMID 36043466, 2022). "The ubiquitous deregulation of the c-Myc (also called MYC) oncogene in human cancers makes it an intriguing therapeutic target." (PMID 35292660, 2022). "Recently, it has been published that the E3 ubiquitin ligase SMURF2 is lowly expressed in CRC, and when overexpressed it targets YY1 for degradation, which results in inhibition of the SENP1/MYC axis and thereby in cancer prevention." (PMID 35887358, 2022).
cancer (continued). "GSEA analysis results demonstrated that multiple cancer-related pathways (such as G2M checkpoint, MYC targets, E2F targets, and KRAS) were upregulated for LIHC with high RPPF19 expression." (PMID 35252202, 2022). "Our recent preclinical studies with the first-generation BTK/PI3K/BRD4 inhibitor SRX3262 in MCL demonstrated reduced phosphorylation of MYC at Ser62 and Thr58, which are critical mediators of MYC protein stability and degradation in cancer." (PMID 35743155, 2022). "MYC is a regulator of ~15% of the genome and plays an essential role in normal and cancer cells, promoting cell proliferation, growth, adhesion, metabolism, angiogenesis, differentiation and apoptosis." (PMID 35267409, 2022). "Human c-Myc protein (from now on indicated as Myc) is a pleiotropic transcription factor encoded by the MYC gene, which is often amplified in cancer." (PMID 36499669, 2022). "c-MYC is frequently described as a target of aberrant transcriptional upregulation due to epigenetic changes in cancer." (PMID 36313707, 2022). "CDK16 knockdown also leads to a reduced expression of MYC and membrane programmed cell death‐ligand 1 (PD‐L1), two possible factors contributing to cancer cell senescence and immunotherapy effects, respectively." (PMID 34687270, 2022). "Common anti-cancer drugs (e.g., chemotherapeutics) often trigger both apoptotic pathways, thereby increasing their reliance on MYC." (PMID 36012403, 2022). "In most cancers, MYC expression is elevated; high MYC expression indicates poor prognosis in patients with ALL." (PMID 35795049, 2022). "The MYC gene family, including MYC, N-MYC and L-MYC, has been confirmed to be highly expressed in various cancers." (PMID 36406346, 2022). "Overall, deregulation of c-MYC not only drives an oncogenic signaling in cancer cells, but also impinges on the TME by linking cellular signaling pathways, EMT, and the TME." (PMID 36483040, 2022). "We observed similar cancer-specific H3K4me3-BDs associated with hijacking of super-enhancers of other common oncogenes in B cell (MAF, MYC, and FGFR3/NSD2) and T cell malignancies (LMO2, TLX3, and TAL1)." (PMID 34933939, 2022). "Overexpression of c-MYC in cancers leads to extracellular matrix (ECM) degradation and promotes angiogenesis, which in turn contributes to malignant invasion and metastasis." (PMID 36483040, 2022). "Studies have demonstrated that several oncogenes, including K-RAS and c-MYC, induce intracellular ROS to promote cancer cell proliferation." (PMID 35359388, 2022). "Increasing evidence reveals that c-MYC has a specific role in cancer stem cells and its epigenetic reprogramming increases the cancer stem cells phenotypes." (PMID 36362070, 2022). "The unique multinuclear, terminally differentiated postmitotic nature of muscle fibers likely explains how muscle is resistant to developing cancer and why sustained MYC is tolerated in this tissue." (PMID 36150502, 2022). "BC200 ncRNA, which also presents evidence of gene-level correlation with POLR3G availability, has been similarly reported to be enhanced by MYC and essential for viability and proliferation in cancer contexts." (PMID 35637192, 2022). "Although the relevance of MXI1 to cancer metastasis remains unexplored, our data, together with the previous observations that MYC and E2F1 promote epithelial-mesenchymal transition and metastasis, implicate MXI1 in metastasis-suppression." (PMID 35149728, 2022). "The MYC gene is amplified in several human cancers and overexpressed in up to 70% of viral and alcohol-related HCC." (PMID 36433941, 2022). "Overexpression of MYC helps cancer cells maintain their unregulated proliferative characteristics, and its down-regulation can reverse this effect." (PMID 34448104, 2022). "In conclusion, OM-153 functions as a potent cell type–dependent inhibitor of WNT/β-catenin, YAP and MYC signaling and can reduce cell growth in a subset of human cancer cell lines in cell culture." (PMID 36873622, 2022).